MYADM (myeloid associated differentiation marker)
Diseases named in the same sentence as MYADM in open-access papers (continued):
Sharing a sentence is not in itself a finding about the gene and the disease.
cancer (5 papers, 2008 to 2025). A tumor composed of atypical neoplastic, often pleomorphic cells that invade other tissues. "MYADM, myeloid-associated differentiation marker is a membrane protein implicated in differentiation and cancer." (PMID 19079774, 2008). "Specifically, genes such as CFD and MYADM primarily function as prognostic biomarkers, playing a crucial role in predicting the prognosis and clinical outcomes of cancer patients." (PMID 40429821, 2025). "After pan-cancer analysis, it was found that the expression levels of MYADM in different cancer types were different, some of which were up-regulated and others were down-regulated, indicating that MYADM plays multiple roles in pan-cancer." (PMID 36061144, 2022). "The MYADM expression differed across many types of cancer and had the potential to serve as a pan-cancer marker." (PMID 36061144, 2022). "It has been shown that the expression of MYADM was different across various types of cancer, which indicates that MYADM has the potential of being a pan-cancer biomarker." (PMID 36061144, 2022). "MYADM is upregulated in multiple cancer types; however, the oncogenic mechanism by which MYADM promotes ESCC remains largely unknown." (PMID 39247591, 2024). "Moreover, a recent study reported high levels of MYADM in multiple cancer types." (PMID 39247591, 2024). "MAL (LUAD, THYM, and UCEC), MAL2 (BRCA, PAAD, and UCEC), and PLLP (KICH, KIRC, and UCEC) present strong correlations (p ≤ 0.001) in three types of cancer, and MALL (KIRC and PAAD), CMTM8 (KIRC and KIRP), and MYADM (LUSC and THYM) do so in two cancer types." (PMID 37345137, 2023).
infection (3 papers, 2023 to 2024). The state of being infected such as from the introduction of a foreign agent such as serum, vaccine, antigenic substance or organism. "Here, we use genome-scale CRISPR/Cas9 screening in human cells and identify myeloid-associated differentiation marker (MYADM) as an essential host factor for PeV-A1, PeV-A2 and PeV-A3 infection." (PMID 38658526, 2024). "While both rodent wild type cells were refractory to PeV-A1-GFP infection, expression of human MYADM rendered both cell lines susceptible to infection." (PMID 38658526, 2024). "In this study, we use a genome-wide gene-knockout strategy in PeV-A3-susceptible cells to identify human myeloid-associated differentiation marker (MYADM), a multi-membrane spanning protein, as a host factor essential for PeV-A3 entry and infection." (PMID 37002207, 2023). "Using immunoprecipitation, we show that MYADM binds to PeV-A1 particles via its fourth extracellular loop, and we identify critical amino acid residues within the loop that mediate binding and infection." (PMID 38658526, 2024). "We show that MYADM is required for viral entry in cell lines and confirm that MYADM mediates infection in human gastrointestinal epithelial organoids representing a primary site of PeV-A infection." (PMID 38658526, 2024). "Together, these results show that MYADM is essential for infection by multiple PeV-A genotypes and that MYADM expression can be rate limiting for infection." (PMID 38658526, 2024). "MYADM from species whose amino acid sequence were more closely related to human (i.e. macaque, cat and dog) acted to functionally restore infection, while more distant species (i.e. mouse, bovine, horse, ferret and goat) failed to do so." (PMID 38658526, 2024). "MYADM was required for PeV-A1, PeV-A2 and PeV-A3 infection of diverse cell types including primary intestinal epithelial cells, which represent a tissue type relevant for parechovirus pathogenesis and fecal-oral transmission." (PMID 38658526, 2024). "Infection of PeV-A1-nLuc was prevented in ΔMYADM cells, and trans-complementation of MYADM restored infectivity to levels comparable to wild type cells." (PMID 38658526, 2024). "The infection of six PeV-As (PeV-A1 to PeV-A6) to human cells is abolished by knocking out the expression of MYADM." (PMID 37002207, 2023). "Upon infection with RV-1B, human AECs grown at an air–liquid interface had increased the MYADM expression predominantly detected in ciliated cells." (PMID 37638015, 2023). "The identification of human MYADM as a factor required for the infection of six PeV-As is therefore expected to facilitate the overall understanding of the pathogenesis of PeV-A infection." (PMID 37002207, 2023). "The identification of MYADM as an essential entry factor for PeV-As infection is expected to advance our understanding of the pathogenesis of PeV-As." (PMID 37002207, 2023). "Thus, MYADM is a critical factor for PeV-A1 and A2 infection in multiple human cell lines as well as in primary epithelial organoids derived from human intestinal tissue." (PMID 38658526, 2024). "Conversely, human MYADM with the hamster extracellular loop lost its ability to mediate infection." (PMID 38658526, 2024). "Notably, ΔMYADM cells were also refractory to infection by PeV-A3, indicating that MYADM is essential for this integrin-independent strain." (PMID 38658526, 2024). "Changing the three amino acids in human MYADM to the horse sequence negated the ability to support infection, while changing these residues in horse MYADM to the human sequence allowed virus replication at levels comparable to human MYADM as determined using PeV-A1-nLuc." (PMID 38658526, 2024). "We next assessed whether TLR3 stimulation increased MYADM expression as we observed with live RV1B infection." (PMID 37638015, 2023). "In addition, besides PeV-A3, at least five other PeV-A genotypes use MYADM as an essential host factor for infection." (PMID 37002207, 2023).
infection (continued). "Moreover, MYADM expression in differentiated human primary epithelial cells (AECs) at air–liquid interface (ALI) cultures also increased upon RV-1B infection." (PMID 37638015, 2023). "We observed significant reductions in several key inflammatory cytokines and effector proteins when MYADM was knocked down—whether in the context of infection or in naïve conditions." (PMID 37638015, 2023). "Therefore, we investigated the role of MYADM in the infection of PeV-A3 (Niigata-423/13), which was isolated from PeV-A3-infected individuals and cultured for a short period of time." (PMID 37002207, 2023). "Furthermore, in HuTu-80 cells, productive infection with these five PeV-As was abrogated by MYADM-KO." (PMID 37002207, 2023). "Taken together, the present results suggest that the differential expression of MYADM by cell type may play an important role in the tissue-specific infection of PeV-A3." (PMID 37002207, 2023). "Human MYADM binds to the VP0 capsid protein of PeV-A3, and the fourth extracellular region of MYADM is essential for the binding of MYADM with VP0 and productive infection of PeV-A3." (PMID 37002207, 2023). "While the ability of mouse cells (MEFs) to support PeV-A1-nLuc infection was strictly dependent on the expression of human MYADM when infected with PeV-A1-nLuc particles, no such dependence was found upon transfection with PeV-A1-nLuc replicon RNA." (PMID 38658526, 2024). "Consistent with the inability of MEF cells to support infection, mouse MYADM did not rescue PeV-A1 infection." (PMID 38658526, 2024). "In contrast, while MYADM knockout drastically reduced infection, it did not prevent binding and internalization of PeV-A1 in A549 cells." (PMID 38658526, 2024). "The expression of human MYADM in hamster cells (BHK-21), which are not susceptible to PeV-A3 infection, induces productive infection with PeV-A3." (PMID 37002207, 2023). "The infection led to increased MYADM mRNA by 2.3-fold, whereas RV-1B infection was not able to induce further MYADM upregulation in MYADM-silenced cells." (PMID 37638015, 2023). "We discovered that Rhinovirus A (RV-1B), and not RSV, infection led to increases of MYADM expression in both H1Hela cells and differentiated primary bronchial epithelial cells (AEC)." (PMID 37638015, 2023). "Infection with the unrelated virus herpes simplex virus (HSV) was not affected by MYADM knockout." (PMID 38658526, 2024). "Based on these results, we speculated that the difference in the fourth extracellular domain of MYADM between humans and hamsters may determine an infection in human cells, but not in hamster BHK-21 cells with PeV-A3." (PMID 37002207, 2023). "Five human cell lines of different origins showed productive PeV-A3 infection; all of these cell lines expressed MYADM, while one cell line with no detectable MYADM expression showed no infection, suggesting that the expression of MYADM determines PeV-A3 infection in cells of different origins." (PMID 37002207, 2023). "Likewise, knockout of MYADM in human cells (293FT) did not decrease replication of the PeV-A1-nLuc replicon nor did MYADM overexpression enhance it, which was in stark contrast to infection using PeV-A1-nLuc virus." (PMID 38658526, 2024). "At the 0.5 multiplicity of infection (MOI), cells expressing MYADM increased twofold compared with those of non-infected controls." (PMID 37638015, 2023). "Furthermore, infection with PeV-A3-EGFP induced the expression of EGFP and CPEs in BHK-21 cells expressing human MYADM (NF-MYADM) or F-MHM, but not mouse MYADM (MF-MYADM) or F-HMH." (PMID 37002207, 2023).
MYADM also shares sentences with these, for which no sentence is quoted: Allergy (2 papers); acute myeloid leukemia (1); bladder urothelial carcinoma (1); breast carcinoma (1); cervical squamous cell carcinoma (1); COVID-19 (1); diffuse large B-cell lymphoma (1); endocervical adenocarcinoma (1); esophageal carcinoma (1); glioma (1); hypothyroidism (1); lung squamous cell carcinoma (1); lymphoid neoplasm (1); metastatic melanoma (1); pancreatic adenocarcinoma (1); pancreatic cancer (1); pancreatic ductal adenocarcinoma (1); pulmonary hypertension (1); rheumatoid arthritis (1); Salmonella Infections (1); stomach adenocarcinoma (1); testicular germ cell tumor (1); thymoma (1); type 1 diabetes (1); uterine carcinosarcoma (1); uterine corpus endometrial carcinoma (1).